RNU6-1120P (RNA, U6 small nuclear 1120, pseudogene)
Gene: Small nuclear RNA gene on chromosome 3 (178,007,672 to 178,007,779, reverse strand). Ensembl gene ENSG00000199858.
Homologues: Orthologues: chimpanzee U6 (100% identical), macaque U6 (95% identical). Paralogues in human: RNU6-1152P (83% identical), RNU6-211P (81% identical), RNU6-768P (81% identical), RNU6-1145P (81% identical), RNU6-16P (81% identical), RNU6-393P (81% identical), RNU6-41P (81% identical), RNU6-732P (81% identical), RNU6-753P (81% identical), RNU6-854P (81% identical), RNU6-1031P (80% identical), RNU6-1047P (80% identical), and 1290 more.